BRD9 (bromodomain containing 9)
Description:
Plays a role in chromatin remodeling and regulation of transcription. Acts as a chromatin reader that recognizes and binds acylated histones: binds histones that are acetylated and/or butyrylated. Component of SWI/SNF chromatin remodeling subcomplex GBAF that carries out key enzymatic activities, changing chromatin structure by altering DNA-histone contacts within a nucleosome in an ATP-dependent manner. Also orchestrates the RAD51-RAD54 complex formation and thereby plays a role in homologous recombination (HR).
Synonyms: FLJ13441; SMARCI2; LAVS3040; PRO9856
Tractability: Small molecule: a structure with a bound ligand is known; a high-quality ligand is known; it has a binding pocket of medium quality. PROTAC: it is named in the literature on targeted protein degradation; UniProt records ubiquitination sites on it; ubiquitination databases record sites on it; its protein half-life has been measured; a small molecule that binds it is known.
Target class: Epigenetic regulator; Bromodomain; Reader
Chemical probes: BI-7273 (high quality), BI-9564 (high quality), I-BRD9 (high quality), LP99 (high quality), TP-472 (high quality), VZ185 (high quality), dBRD9 (high quality), dBRD9-A (high quality)
Gene: Protein-coding gene on chromosome 5 (850,291 to 892,838, reverse strand). Ensembl gene ENSG00000028310.
Subcellular location: Nucleus
Subcellular location (Human Protein Atlas): Nucleoplasm
Pathways (Reactome):
Chromatin organization: Formation of the non-canonical BAF (ncBAF) complex
Gene Ontology:
Molecular function: histone reader activity; protein binding; protein-macromolecule adaptor activity; nucleic acid binding
Biological process: double-strand break repair via homologous recombination; chromatin remodeling; negative regulation of cell differentiation; positive regulation of cell population proliferation; positive regulation of stem cell population maintenance; regulation of transcription by RNA polymerase II
Cellular component: nucleoplasm; nucleus; site of double-strand break; SWI/SNF complex; chromatin; GBAF complex
Genetic constraint (gnomAD): Loss-of-function variants: 43 observed, 59.79 expected, observed/expected ratio (o/e) 0.72, 90% interval 0.56 to 0.93. The upper end of that interval is the gene's LOEUF score, 0.93, which puts it in group 3 of 6, group 1 being the genes least tolerant of losing a copy. Missense variants: 665 observed, 709.67 expected, observed/expected ratio (o/e) 0.94, 90% interval 0.88 to 1. Synonymous variants: 313 observed, 277.01 expected, observed/expected ratio (o/e) 1.13, 90% interval 1.03 to 1.24.
Homologues: Orthologues: macaque BRD9 (99% identical), chimpanzee BRD9 (98% identical), guinea pig BRD9 (94% identical), dog BRD9 (94% identical), rat Brd9 (93% identical), mouse Brd9 (92% identical), pig BRD9 (90% identical), rabbit BRD9 (88% identical), tropical clawed frog brd9 (72% identical), zebrafish brd9 (71% identical), Drosophila melanogaster Brd7-9 (34% identical), Caenorhabditis elegans swsn-9 (23% identical). Paralogues in human: BRD7 (36% identical), YBEY (6% identical).
Diseases named in the same sentence as BRD9 in open-access papers:
BRD9 is named in the same sentence as 116 diseases in open-access papers, as found by Europe PMC text mining. Sharing a sentence is not in itself a finding about the gene and the disease. The quoted sentences say what the papers report.
synovial sarcoma (26 papers, 2018 to 2025). "FHD-609 is a CRBN-based BRD9 degrader that is administered intravenously and is currently in Phase I clinical trials for patients with advanced synovial sarcoma or advanced SMARCB1-deficient tumors." (PMID 38390898, 2024). "On these grounds, BRD9 targeting using PROTAC degraders is currently under investigation in a phase 1 clinical trial (NCT04965753) in patients with advanced synovial sarcoma or advanced SMARCB1-loss tumors." (PMID 39261602, 2024). "Preclinical studies have shown that CFT8634 is both potent and selective in degrading BRD9 in synovial sarcoma and SMARCB-1-deficient cases, demonstrating a DC50 value of 2.7 nM." (PMID 38675453, 2024). "BRD9 is found overexpressed in numerous cancers and this overexpression seems to be associated with susceptibility to lung cancer, synovial sarcoma, and breast cancer, indicating that BRD9 has a potential oncogenic effect." (PMID 32276436, 2020). "Another study demonstrated that the inhibition of BRD9 acted in a synthetic lethal manner in cBAF-deficient cancer, and the inhibitor of BRD9 effectively decreased the proliferation of cancer cells in synovial sarcoma and malignant rhabdoid tumors." (PMID 31504061, 2019). "Similar to the findings in rhabdoid tumours, ncBAF also seems to play a significant role in synovial sarcoma as cell lines of this tumour entity are sensitive to the loss of BRD9, BAF60A or GLTSCR1." (PMID 30898143, 2019). "We demonstrate that BRD9 supports oncogenic mechanisms underlying the SS18-SSX fusion in synovial sarcoma and highlight targeted degradation of BRD9 as a potential therapeutic opportunity in this disease." (PMID 30431433, 2018). "We show that BRD9 is part of SS18-SSX containing BAF complexes in synovial sarcoma cells; and that the association of BRD9 with the BAF complex is functionally essential." (PMID 30431433, 2018). "Furthermore, recent studies indicate that tumors deficient in SMARCB1, like synovial sarcoma and malignant rhabdoid tumors, exhibit a synthetic lethal dependency on BRD9." (PMID 38675453, 2024). "dBRD9 suppressed oncogenic gene expression and induced synthetic lethality in synovial sarcoma cells more effectively than the parent compound, BI-7273, suggesting that a complete loss of the BRD9 protein is more deleterious than the sole inhibition of the bromodomain." (PMID 38390898, 2024). "In the area of solid tumors, CFT8634, a BRD9 degrader by C4 Therapeutics, is being evaluated in Phase 1 trials for synovial sarcoma, a rare and aggressive soft tissue malignancy." (PMID 40574056, 2025). "A single oral dose of CW-3308 efficiently reduces BRD9 protein levels by >90% in synovial sarcoma HS-SY-II xenograft tumor tissue." (PMID 40115023, 2025). "Multilayered regulation of EMT factors by SS18::SSX and BRD9 contributes to the cellular phenotype in synovial sarcoma." (PMID 41440042, 2025). "Increased BRD9 incorporation into the ncBAF complex has been reported in SMARCB1-mutated sarcoma cell lines and demonstrated to induce synthetic lethality in synovial sarcoma and rhabdomyosarcoma cell lines with perturbed SMARCB1." (PMID 39261602, 2024). "CFT-8634 is a BiDACTM degrader targeting BRD9 for the treatment of BRD9-dependent cancers, including synovial sarcoma and SMARCB1-deleted cancers." (PMID 38256933, 2024). "We also describe artificial adjuvant vector cells (aAVCs) and BRD9 inhibitors, two additional potential targets for treatment of advanced synovial sarcoma." (PMID 36761952, 2023). "CFT8634 is an orally bioavailable degrader against BRD9 for the treatment of synovial sarcoma and SMARCB1-deleted solid malignancies." (PMID 36499765, 2022). "FHD-609 (NCT04965753), which acts as a BRD9 target, is also being studied in Synovial sarcoma cases." (PMID 36557960, 2022). "A clearer example for the potential therapeutic advantages of bromodomain-protein degradation are the pre-clinical observations made in synovial sarcoma regarding targeting of BRD9." (PMID 33371192, 2020).
synovial sarcoma (continued). "Consistently, a PROTAC targeting the BRD9 subunit of the BAF complex has already shown promise in models of synovial sarcoma." (PMID 31217031, 2019). "Consistent with our genetic data, synovial sarcoma cells were more sensitive to BRD9 bromodomain inhibition compared to other pediatric sarcomas." (PMID 30431433, 2018). "As such by combining genomic and proteomic approaches we have identified BRD9 as a functional dependency within SS18-SSX fusion protein containing BAF complexes in synovial sarcoma cells." (PMID 30431433, 2018). "Our data indicate that through assembly into SS18-SSX containing complexes BRD9 supports oncogenic gene expression programs necessary for synovial sarcoma oncogenesis." (PMID 30431433, 2018). "Remarkably, synovial sarcoma cells are highly sensitive to a novel small molecule degrader of BRD9, while other sarcoma subtypes are unaffected." (PMID 30431433, 2018). "BRD9 is a component of SS18-SSX containing BAF complexes in synovial sarcoma cells; and integration of BRD9 into these complexes is critical for cell growth." (PMID 30431433, 2018). "Targeting BRD9 with a novel chemical degrader specifically impedes synovial sarcoma cell viability; eliciting more robust therapeutic effects than BRD9 inhibition using bromodomain targeting chemical probes." (PMID 30431433, 2018). "Consistent with this, within the recently published Project DRIVE database we observe, that among the almost 400 cancer cell lines assayed, synovial sarcoma cell lines are the most sensitive to BRD9 targeting." (PMID 30431433, 2018). "Remarkably, of the 52 bromodomains contained within 38 proteins targeted in this library, only the BRD9 bromodomain had all sgRNAs specifically depleted in synovial sarcoma cells." (PMID 30431433, 2018). "This indicates that BRD9, and the BRD9 bromodomain, are selective functional dependencies in synovial sarcoma; highlighting a novel therapeutic target in this disease." (PMID 30431433, 2018). "We demonstrate that degradation of BRD9, a member of an oncogenic multi-protein complex in synovial sarcoma, has a more profound effect on cancer cell survival than small-molecule mediated inhibition." (PMID 30431433, 2018). "Here using a custom CRISPR/Cas9 based functional genomics approach focused on chromatin regulatory genes we identify the bromodomain of BRD9 as a vulnerability in synovial sarcoma cells." (PMID 30431433, 2018). "Using an independent shRNA-based approach we observed similar synovial sarcoma specific effects following knockdown of BRD9 protein levels." (PMID 30431433, 2018). "Using a domain-focused CRISPR screen we identified the bromodomain of BRD9 as a critical functional dependency in synovial sarcoma." (PMID 30431433, 2018). "For example, Bromodomain Containing 9 (BRD9) is crucial for the assembly of SS18-SSX-associated SWI/SNF complex in synovial sarcoma cells, and suppression of BRD9 by chemical degraders has been shown to attenuate tumor growth in a synovial sarcoma xenograft mouse model." (PMID 40296913, 2025). "BRD9 controls key pathways governing synovial sarcoma differentiation." (PMID 41440042, 2025). "At present, several PROTAC drugs have undergone or are undergoing clinical trials, including ARV-110 which targets the androgen receptor in prostate cancer, ARV-471, targeting the estrogen receptor in breast cancer, and FHD-609 which targets BRD9 in Synovial sarcoma." (PMID 36557960, 2022). "A BRD9 specific degrader was developed as a tool compound to study the function of this bromodomain-containing protein, and it was demonstrated that degradation of BRD9 triggered downregulation of oncogenic programs that contribute to the development of synovial sarcoma/soft tissue tumors." (PMID 34298819, 2021). "When utilizing a PROTAC of BRD9 (dBRD9A), the therapeutic efficacy in synovial sarcoma could be substantially improved due to elimination of BRD9 and a suspected higher degree of ncBAF complex disruption." (PMID 33371192, 2020).
synovial sarcoma (continued). "Importantly, genetic targeting of BRD9 using different single-guide RNAs was detrimental for synovial sarcoma cells." (PMID 33371192, 2020). "The dependency of synovial sarcoma on BRD9 could make BRD9 inhibition a promising target for therapy of this cancer entity." (PMID 30898143, 2019). "We’ve shown that BRD9 is an essential SS18-SSX fusion protein co-factor in synovial sarcoma." (PMID 30431433, 2018). "Taken together, our findings highlight BRD9 as a novel therapeutic target in synovial sarcoma." (PMID 30431433, 2018). "Next, we wanted to understand whether BRD9 executes any bromodomain independent functions in synovial sarcoma cells." (PMID 30431433, 2018). "Next, to test whether SS18-SSX fusions also interact with BRD9 in synovial sarcoma cells, we immunoprecipitated the endogenous fusion protein in two independent synovial sarcoma cell lines." (PMID 30431433, 2018). "The BRD9 bromodomain is a functional dependency in synovial sarcoma." (PMID 30431433, 2018). "Indeed, transcriptomic studies indicated that targeting BRD9 could perturb only a very limited subset of SS18-SSX target genes in synovial sarcoma cells." (PMID 40296913, 2025). "As for BRD9, it has shown a “strongly selective” of dependency for these cell lines, which means that some specific cancer types are strongly depended on this gene, such as synovial sarcoma (p value = 2.9e-04) and acute lymphoblastic leukemia (p value = 1.4e-05)." (PMID 31504061, 2019). "However, it is unknown whether BRD9 is part of the oncogenic SS18-SSX containing BAF complex in synovial sarcoma cells." (PMID 30431433, 2018). "BRD9 is a component of the SWI/SNF chromatin remodeling complex, and its degradation disrupts oncogenic transcriptional programs in synovial sarcoma cells, presenting a novel therapeutic avenue." (PMID 40574056, 2025). "PROTACs targeting BRD4 and BRD9, components of the SWI/SNF (BAF) remodelling complex, have also shown efficacy in preclinical MPNST, malignant rhabdoid tumour and synovial sarcoma models." (PMID 40983796, 2025). "Significantly, various pieces of evidence have demonstrated that BRD9 knockdown effectively restrains the proliferation of human acute myeloid leukemia (AML), synovial sarcoma, and malignant rhabdoid tumor (MRT)." (PMID 38543178, 2024). "(B) Pie charts representing the distribution of BRD9 and SS18-SSX1 binding sites on the synovial sarcoma genome." (PMID 30431433, 2018). "Our work demonstrates the importance of BRD9 in supporting SS18-SSX function and oncogenic gene expression in synovial sarcoma cells." (PMID 30431433, 2018). "Comparing the binding profiles of BRD9 and SS18-SSX1 demonstrated that these proteins co-localize extensively on the synovial sarcoma genome." (PMID 30431433, 2018). "To test the feasibility of small-molecule mediated targeting of the BRD9 bromodomain as a therapeutic approach in synovial sarcoma we performed dose response experiments using two independent BRD9 inhibitors, BI7273 and I-BRD9." (PMID 30431433, 2018). "In vitro work has shown that proliferative growth in ATRT and synovial sarcomas is dependent on residual GBAF functional activity and hence targeting selective subunits of the GBAF subcomplex; namely, BRD9 or GLTSCR1 can reduce cellular viability in these solid tumors." (PMID 39125735, 2024). "Highlighting that bromodomain inhibition, while at least partially effective at blocking synovial sarcoma cell growth/survival, is unlikely to completely ablate the functional contributions of BRD9." (PMID 30431433, 2018). "Taken together, these data demonstrate that targeting BRD9 function with chemical degraders, rather than bromodomain inhibitors, is a more efficacious therapeutic approach in synovial sarcoma." (PMID 30431433, 2018). "Furthermore, several links between BRD9 and tumorigenesis have been identified in cancers such as acute myeloid leukemia squamous cell lung cancer (SqCLC), malignant rhabdoid tumors (MRT), and synovial sarcoma (SS)." (PMID 38473159, 2024).
synovial sarcoma (continued). "Moreover BRD9 and SS18-SSX co-localize extensively on the synovial sarcoma genome." (PMID 30431433, 2018). "As opposed to BRD4, BRD9 is a selective dependency in certain cancer types, including AML and synovial sarcoma." (PMID 33371192, 2020). "Bromodomain-containing protein 9 (BRD9), a specific component of the non-canonical mammalian SWI/SNF chromatin remodelling complex, is essential to maintain the transformed phenotype of acute myeloid leukemia and the growth of synovial sarcoma." (PMID 36499765, 2022).
acute myeloid leukemia (24 papers, 2017 to 2025). Acute myeloid leukemia (AML) is a group of neoplasms arising from precursor cells committed to the myeloid cell-line differentiation. "Consistent with this, we find that BRD9 is essential for the development and maintenance of acute myeloid leukemia (AML) as its loss remarkably promotes myeloid differentiation with open chromatin at CTCF sites." (PMID 38102116, 2023). "Recurrent focal amplifications of BRD9 have been associated with tumorigenicity in several cancers and inhibition of BRD9 was found to suppress breast, ovarian, gastrointestinal stromal cancer, and prostate tumor growth as well as proliferation of acute myeloid leukemia cells." (PMID 35323214, 2022). "We and others observed a dependency on BRD9 in acute myeloid leukemia (AML), B-cell acute lymphoblastic leukemia (B-ALL), and MM." (PMID 38610997, 2024). "Bromodomain-containing protein 9 (BRD9) has a critical role in human squamous cell lung cancer, acute myeloid leukemia, and malignant rhabdoid tumors." (PMID 32908135, 2020). "The ATPase subunit BRG1 has been shown to bind BRD9 in acute myeloid leukemia (AML) cells and is essential in supporting enhancer-mediated MYC expression in this context." (PMID 31652979, 2019). "Certain types of hematologic cancer cells (e.g., acute myeloid leukemia cells) require BRD9 to sustain MYC transcription, cell proliferation, and a block in differentiation." (PMID 30760718, 2019). "Notably, the BRD9-selective antagonist I-BRD9 has been employed in several types of cancer, including rhabdoid tumors, ovarian cancer, clear cell renal cell carcinoma (ccRCCs), acute myeloid leukemia, and colon adenocarcinoma." (PMID 38255982, 2024). "Here, we used novel small molecule inhibitors and degraders along with RNA interference to assess the dependency on BRD9 in the context of diverse hematological malignancies, including acute myeloid leukemia (AML), acute lymphoblastic leukemia (ALL), and multiple myeloma (MM) model systems." (PMID 35853853, 2022). "Additionally, BRD9 chromatin-binding also regulates cancer cell proliferation and tumorigenicity in acute myeloid leukaemia, indicating its oncogenic role in transformed blood cells." (PMID 32276436, 2020). "BRD4 and BRD9 have been reported to co-localize at the Myc super enhancer in the mouse cell line model for acute myeloid leukemia, suggesting that recognition of acetylated BRD4 may be a common mechanism of GBAF complex recruitment." (PMID 30510198, 2018). "A previous report demonstrated that acute myeloid leukemia (AML) cell lines require BRD9 to sustain MYC transcription for leukemia maintenance and proliferation." (PMID 38102116, 2023). "Here we identify bromodomain-containing protein 9 (BRD9) as a critical target required in acute myeloid leukemia (AML)." (PMID 31000698, 2019). "BRD9 is unique to the ncBAF complex and its genetic and pharmacological inhibition is reported to induce synthetic lethality in several cancers, including acute myeloid leukemia (AML), synovial sarcoma, non-small cell lung cancer and prostate cancer." (PMID 38816579, 2024). "It has been shown that BRD9 depletion (at the mRNA and protein level) upregulates SOCS3, which, in turn, inhibits STAT5, reducing JAK-STAT pathway activation in acute myeloid leukaemia." (PMID 34944438, 2021). "In acute myeloid leukemia (AML) cells, BRD9 depletion resulted in G1 arrest." (PMID 28714904, 2017). "Bromodomain-containing protein 9 (BRD9), a SWI/SNF subunit, participates in the proliferation of acute myeloid leukemia (AML) cells." (PMID 35402370, 2022). "The non-canonical BAF complex (ncBAF) subunit BRD9 is essential for acute myeloid leukemia (AML) cell viability but has an unclear role in leukemogenesis." (PMID 38126767, 2024).